RNU4-1 (RNA, U4 small nuclear 1)
Synonyms: U4BL; U4; RNU4A; RNU4B2
Gene: Small nuclear RNA gene on chromosome 12 (120,293,093 to 120,293,237, reverse strand). Ensembl gene ENSG00000200795.
Pathways (Reactome):
Gene expression (Transcription): RNA polymerase II transcribes snRNA genes
Gene Ontology:
Molecular function: U6 snRNA binding
Biological process: formation of quadruple SL/U4/U5/U6 snRNP; spliceosomal tri-snRNP complex assembly
Cellular component: U4 snRNP; U4/U6 x U5 tri-snRNP complex